CXCL12 (C-X-C motif chemokine ligand 12)
Diseases named in the same sentence as CXCL12 in open-access papers (continued):
Sharing a sentence is not in itself a finding about the gene and the disease.
follicular lymphoma (8 papers, 2011 to 2025). Follicular lymphoma is a form of non-Hodgkin lymphoma characterized by a proliferation of B cells whose nodular structure of follicular architecture is preserved. "The published RNA sequencing data of FRCs show activation of chemokine signaling after co-culture with DLBCL cells, and in follicular lymphoma (FL), another type of B-cell lymphoma, CXCL12 production by FL-CAFs was shown to promote tumor cell migration." (PMID 40061210, 2025). "In follicular lymphoma (FL), fibroblastic reticular cells secrete stromal-derived growth factor 1 (SDF-1, also known as CXCL12), which stimulates follicular T-helper cells (TFHs) that support malignant cell growth through CD40–CD40L interactions." (PMID 33804869, 2021). "CXCL12+ stromal cells derived from both bone marrow and tonsils (LN-like FRCs) of healthy donors can attract malignant B cells and appear to enhance the survival of follicular lymphoma B cells compared with healthy B cells isolated from blood." (PMID 29482663, 2018). "In addition, extracellular vesicles (EVs) produced by follicular lymphoma B-cells have been shown to promote the polarization of BM-derived MSCs to secrete such factors as CXCL12 that could constitute in turn a BM follicular lymphoma permissive stromal niche." (PMID 34858421, 2021). "Recently, the CXCL12/CXCR4 axis was reported to function through p38 MAPK signaling to drive the progression and metastasis of various cancers, including follicular lymphoma and lung, thyroid, colorectal and breast carcinomas." (PMID 31434952, 2019). "We determined the expression levels of CXCR4, CXCR7, and their ligand CXCL12 in NGCB- and GCB-DLCBLs consisting of primary and transformed follicular lymphomas (n = 71 in total) and germinal center B cells (GC-B, n = 5) serving as non-neoplastic controls by using RQ-PCR." (PMID 31554271, 2019).
invasive breast carcinoma (8 papers, 2010 to 2023). A carcinoma that infiltrates the breast parenchyma. "CXCL12, produced by stromal fibroblasts within invasive breast cancers, promotes angiogenesis and has additionally been associated with increased macrophage density in tumors." (PMID 24156623, 2013). "Similarly, in invasive breast carcinomas, stromal fibroblasts are shown to promote tumor growth and angiogenesis through elevated SDF-1/CXCL12 secretion." (PMID 36672620, 2023). "To do this, we patterned cells to mimic the disorganization of CXCL12+, CXCR4+, and CXCR7+ cells observed in invasive breast cancer." (PMID 25909600, 2015). "Co-injection of breast cancer cells and fibroblasts also promotes the progression of ductal carcinoma in situ to invasive breast carcinoma by stimulating chemokine (C-X-C motif) ligand 14 (CXCL14) and chemokine (C-X-C motif) ligand 12 (CXCL12) production." (PMID 25060643, 2014).
liver disease (8 papers, 2012 to 2025). "It was observed that AR, CREB1, ACVR2A, and CXCL12 were down-regulated in T1DM-associated liver disease; however, they exhibited up-regulation after NAC treatment." (PMID 40001479, 2025). "Therefore, whether NAC’s regulation of CXCL12 in the treatment of T1DM liver disease is linked to chemokine function remains a critical question that merits further investigation." (PMID 40001479, 2025). "Inflammatory chemokines, such as CXCL12, play a key role in liver disease by regulating immune responses and influencing fibrosis." (PMID 40371331, 2025). "CXCL12, also called stromal cell-derived factor 1 (SDF-1), is a chemokine constitutively expressed by biliary epithelial cells, of which the expression is enhanced in liver diseases like PSC, at least in end-stage disease." (PMID 32743534, 2020). "Expression of the chemokine CXCL12 on biliary epithelial cells is low in normal liver, but enhanced in inflammatory diseases of the liver such as PSC, PBC and HCV." (PMID 32743534, 2020). "During the process of liver disease in T1DM, liver cells are impaired, and the expression of CXCL12 is downregulated." (PMID 40001479, 2025). "Because CXCL12 and CXCR4/CXCR7 play important roles in liver homeostasis and regeneration, their expression has complex interactions in the pathogenesis of liver diseases." (PMID 38767772, 2024). "The increased CXCL12, HLECS+ lymphocytes, and CD4+ lymphocytes in the presence of active liver disease in 11 HIV-1 infected patients suggests a potential regulatory axis between the liver and hematopoietic tissue that may include additional unknown factors." (PMID 22363634, 2012). "Similarly, CXCL1 and CXCL9 have chemotactic activities and roles in angiogenesis, inflammation and tumor genesis, CXCL12 is related to the HCC metastatic network by recruiting endothelial cell tumor progenitors, and PECAM-1 reflects the liver disease progression." (PMID 26226632, 2015).
myelofibrosis (8 papers, 2014 to 2024). A partial or complete replacement of the bone marrow stroma by fibrous tissue. "The mild extracellular staining was in line with CXCL12 functions, which, however, is another reason preventing it to be a useful diagnostic biomarker of myelofibrosis progression." (PMID 35356507, 2022). "Here, we tested whether the expression growth related biomarkers L-NGFR/CD271, phospho-ERK1-2 and CXCL12 can be linked to the functional activation of bone marrow stromal cells during primary myelofibrosis progression." (PMID 35356507, 2022). "The per cell expression of NSF, in particular Cxcl12 and Csf1, was markedly decreased in myelofibrosis vs. control bone marrow MSCs but increased in fibroblasts at transcript level." (PMID 39383242, 2024). "CXCL12/CXCR4 pathway is activated by oncogenic JAK2, which frequently suffers activating mutations in primary myelofibrosis." (PMID 35356507, 2022). "Recent data show that RNA expression of key niche factors, including Kitlg and Cxcl12, is reduced in bone marrow MSCs from mouse models of MPNs and from patients with myelofibrosis." (PMID 35439167, 2022). "In this study, using immunohistochemistry, we tested the expression of L-NGFR, pER1-2 and CXCL12 proteins, which were primarily expressed in stromal cells in bone marrow biopsies of primary myelofibrosis." (PMID 35356507, 2022). "In line with this, we detected CXCL12 positive perivascular and peri‐osteoblastic stromal cells at increasing density with the Gomori’s silver staining based myelofibrosis grades." (PMID 35356507, 2022). "Accordingly, primary myelofibrosis (MF) patient cells demonstrate an increased CXCL12-induced chemotaxis when compared to controls." (PMID 28903325, 2017). "Myelofibrosis, featured by increased stromal cell activation, may also involve CXCL12 upregulation, which can contribute to protecting leukemic stem cells." (PMID 35356507, 2022). "The CXCL12/CXCR4 pathway can be induced by oncogenic JAK2, which frequently suffers activating mutations in primary myelofibrosis, and JAK2 inhibition can reduce the chemotaxis of hematopoietic cells isolated from primary myelofibrosis." (PMID 35356507, 2022). "Therefore, CXCL12 may also be involved in protecting the leukemic stem cells and contributing to myelofibrosis progression, though CXCR4 is downregulated in the malignant progenitors, which may explain extramedullary clonal hematopoiesis in myelofibrosis." (PMID 35356507, 2022). "In conclusion, all of our tested growth related biomarkers including L-NGFR, p-ERK1-2 and CXCL12 were likely to be expressed in activated bone marrow stromal cells and their immunoscores were statistically correlated with Gomori’s silver impregnation based myelofibrosis grades at varying strength." (PMID 35356507, 2022). "Additionally, other CXCR4/CXCL12 inhibitors have shown synergy with ICIs in vitro and these combination regimens are now being assessed in clinical trials for PDAC and myelofibrosis (NCT04177810, NCT02826486, NCT03168139, and NCT04177810)." (PMID 35797269, 2022). "Importantly, upregulation of CXCL12, ASPN, and OLFM3, factors secreted by CAF, has been observed; CXCL12, through the interaction with its receptor CXCR4, can lead to CXCL12 and TGFβ production and concur to myelofibrosis." (PMID 29515580, 2018). "The relative frequency of iFibs was 2-fold higher in myelofibrosis mice than controls, and expression of chemokine genes was strongly enriched in the iFibs with significantly increased per cell expression of chemokines in MPL vs. control fibroblasts, including Kitl, Cxcl12, Ccl2, Cxcl1." (PMID 39383242, 2024).
neutropenia (8 papers, 2009 to 2024). A decrease in the number of neutrophils found in the blood. "As a result, increased neutrophil responsiveness to CXCL12 is thought to drive retention of neutrophils in the bone marrow (myelokathexis), where CXCL12 is highly expressed, leading to their scarcity in the periphery (neutropenia)." (PMID 28928741, 2017). "G-CSF, which downregulates expression of the CXCR4 receptor and its ligand SDF-1/CXCL12, is commonly used to reduce neutropenia in WHIM patients." (PMID 19956569, 2009).
Alzheimer disease (7 papers, 2016 to 2025). A progressive, neurodegenerative disease characterized by loss of function and death of nerve cells in several areas of the brain leading to loss of cognitive function such as memory and language. "A decreased level of CXCL12 in Alzheimer's disease has been documented as affecting cognitive function, impairing learning and memory." (PMID 33869630, 2021). "The chemokine CXCL12 (SDF-1α) controls the functions of bone marrow-derived stem cell functions and neurogenesis and there are decreased level of CXCL12 in early Alzheimer’s disease." (PMID 30096932, 2018). "An exception is that decreased blood levels of CXCL12 are observed in Alzheimer’s disease." (PMID 32098047, 2020). "Interestingly, Alzheimer's disease may eliminate spines in clusters, so CXCL12's modest effect on thin spine clusters could be therapeutically relevant." (PMID 40335156, 2025).
Anxiety (7 papers, 2017 to 2025). Intense feelings of nervousness, tension, or panic often arise in response to interpersonal stresses. "These behavioral results demonstrate that the Cxcl12/Cxcr4 chemokine system has a role in mediating these ethanol-induced changes in locomotor and anxiety-like behaviors." (PMID 36702854, 2023). "Our results are also consistent with findings that LPS injection of adult mice dysregulated CXCL12, which in turn increased glutamatergic release in the amygdala, and anxiety-like behavior occurrence." (PMID 32848554, 2020). "In the OFT, the mice in Sevo + OE CXCL12 group showed a longer total distance traveled, more central visits, longer central distance traveled and duration time compared to the offspring in the Sevo + RFP group, ameliorating anxiety-like behaviors." (PMID 38129829, 2023). "With prenatal HFD exposure known to increase anxiety-like behaviors in offspring, and ENK in the PVN specifically shown to be a positive factor in inducing anxiety, this study tested whether prenatal CXCL12 administration has similar behavioral effects as the HFD." (PMID 28567007, 2017).
B-cell lymphoma (7 papers, 2017 to 2025). "In line with the increased expression of SDF-1/CXCL12, an upregulated expression of the associated chemokine receptor CXCR4 was also detected on EBV-positive NPC, GC and B-cell lymphomas." (PMID 34680337, 2021). "Because B cell lymphomas are enriched for CXCL12-expressing stromal cells, it was possible that the greater efficacy of allo-TCXCR4 in comparison with controls could be linked directly to their increased recruitment to the tumor bed." (PMID 29485974, 2018). "Apart from growth retardation, the CD19 KO cells showed no CXCL12-induced migration, highlighting the critical role of CD19 in maintaining B-cell lymphoma viability and mobility." (PMID 40076664, 2025).
cardiomyopathy (7 papers, 2014 to 2023). A disease of the heart muscle or myocardium proper. "Supporting our data, a recently published study showed that cardiomyocyte specific deletion of the CXCL12 corresponding receptor CXCR4 in mice leads to progressive cardiomyopathy with significant tissue fibrosis." (PMID 34072818, 2021). "The upregulated hub genes ADCY2, CXCL12, and GNB4 were enriched in calcium signal pathway, dilated cardiomyopathy, hypertrophic cardiomyopathy, neuroactive ligand-receptor interaction pathway, and vascular smooth muscle contraction pathways related to cardiomyopathy." (PMID 34603374, 2021).
chronic kidney disease (7 papers, 2014 to 2024). Impairment of the renal function secondary to chronic kidney damage persisting for three or more months. "Analysis of another public chronic kidney disease (CKD) data set also revealed that CXCL12/CXCR4/C3 was highly correlated with the severity of CKD." (PMID 38716725, 2024).
Cirrhosis (7 papers, 2015 to 2025). A chronic disorder of the liver in which liver tissue becomes scarred and is partially replaced by regenerative nodules and fibrotic tissue resulting in loss of liver function. "In response to CXCL12, cells (such as HSCs) expressing CXCR4 can participate in fibrosis and cirrhosis through migration and activation." (PMID 34386499, 2021). "CXCR4 (AUC = 0.941), COL1A2 (AUC = 0.919), CCR7 (AUC = 0.878), COL1A1 (AUC = 0.853), CXCL12 (AUC = 0.848), and CXCL8 (AUC = 0.828) had similar AUC values, demonstrating that the identified hub genes exhibited a reliable discriminatory capacity as potential biomarkers for cirrhosis." (PMID 41223189, 2025). "Upon detailed assessment, cytokine levels and cirrhosis etiology revealed that HBV-cirrhosis—regardless of antiviral therapy—had a 3-fold increase in IFN-γ, TRAIL and CXCL1 (GRO-α) levels and up to 3-fold decrease in MMP-2, CXCL12, IL2RA, IL-6Rα, CCL2 (MCP1) and CCL21 (6kine) levels." (PMID 36230823, 2022).
dyslipidemia (7 papers, 2021 to 2026). "CXCL12 was closely associated with AS progression, and elevated expression of CXCL12 was involved in various AS pathological processes, such as dyslipidemia, inflammation, neointima hyperplasia and angiogenesis." (PMID 33932991, 2021). "Altered levels of distinct chemokines, like CCL5/RANTES, CXCL12/SDF-1a, CCL7/MCP-3, CCL2/MCP-1, CXCL1/GROa, and the eotaxin family, contribute to the development and/or exacerbation of inflammation, which is a common feature of numerous skin diseases as well as metabolic syndrome." (PMID 42042898, 2026).
Ewing sarcoma (7 papers, 2012 to 2025). A small round cell tumor that lacks morphologic, immunohistochemical, and electron microscopic evidence of neuroectodermal differentiation. "Accordingly, targeting the CXCL12/CXCR4 axis inhibited the metastatic capability of Ewing sarcoma cells." (PMID 34440844, 2021). "Lungs and bone (marrow), organs of predilection for (primary/metastatic) Ewing sarcoma, represent predominant CXCL12 sources." (PMID 23249693, 2012). "Indeed, a prior study showed that CXCL12 promotes the proliferation of CXCR4 positive Ewing sarcoma cells in vitro and the same study also identified a positive correlation between tumor volume and the presence of CXCR4 positive tumor cells in primary human tumors." (PMID 27528222, 2016). "In Ewing sarcoma, there were 21 significant relationships, including IL-4/IL-1β (r2 = 0.55, p = 0.00048), IL-4/IL-8 (r2 = 0.68, p = 0.0000047), CXCL14/IL-15 (r2 = 0.61, p = 0.00013), and CXCL5/CXCL12 (r2 = 0.64, p = 0.000030)." (PMID 41008853, 2025). "In contrast, CXCL12 (SDF-1α) ligand did not affect Ewing sarcoma cell proliferation as a single agent or alter the proliferative effects of plerixafor." (PMID 29776413, 2018). "Moreover, many pediatric neuroblastoma, Ewing sarcoma (ES), osteosarcoma, and ALL, show altered expression of circulating cytokines/chemokines such as CCL2, CXCL4, CXCL6, CXCL10, and CXCL12." (PMID 38927907, 2024).
gastric tumor (7 papers, 2014 to 2024). "Homeostatic chemokines play a central role in the development of secondary lymphoid organs and TLSs,4, 12 and our earlier data revealed transcripts for Cxcl13, Ccl19, Ccl21 and Cxcl12 in laser microdissected TLSs from 6‐month‐old gp130F/F mice with well‐established gastric tumours." (PMID 29417587, 2018). "In gastric tumor samples, elevated levels of DARPP-32, CXCR4, and CXCL-12 were noted compared to normal tissues, with statistical analysis confirming positive correlations between DARPP-32 and both CXCR4 and CXCL-12." (PMID 39767693, 2024). "In comparison with non-tumor tissue, gastric tumors could secrete more CXCL12, which attracted migration of mast cells." (PMID 30808413, 2019).
head and neck cancer (7 papers, 2014 to 2025). A primary or metastatic malignant neoplasm affecting the head and neck. "In contrast to these results, the same group also demonstrated that in the head and neck cancer cell line UMSCC-11A CD44+/CXCR4+ cells showed increased podia formation with the additional of CXCL12 suggesting a role of this axis in the regulation of CD44+ CSC." (PMID 35047489, 2021). "Lower expression of CXCL12 was also reported in head and neck cancer due to hypermethylation in promoter region." (PMID 27597234, 2016). "In naïve CD8+ T-cells, dopamine (10−7M) potentiated homing to CCL19, CCL21, and CXCL12 through D3 and Gαi-mediated Ca2+ mobilization, and treating peripheral T-cells from head and neck cancer patients with dopamine (10−8M) increased spontaneous migration and migration toward CXCL12." (PMID 36757901, 2023).
Hypercholesterolemia (7 papers, 2012 to 2023). An increased concentration of cholesterol in the blood. "In the present study, we first showed that long-term supplementation with purified anthocyanins reduced the plasma levels of the platelet chemokines CXCL7, CXCL5 and CXCL12 in subjects with hypercholesterolemia." (PMID 27933092, 2016). "Additionally, treatment of hypercholesterolemia with high-doses statins results in a decrease in circulating CXCL12 levels, which are inversely correlated with the administered dose of statin." (PMID 34207596, 2021).
kidney damage (7 papers, 2018 to 2024). "The CXCL12/CXCR4 pathway can promote chronic allogeneic nephropathy progression and fibrosis by recruiting bone marrow-derived cells to the kidney." (PMID 39192987, 2024). "In fact, a series of studies showed that these two respective chemokine targets mediate different pathomechanisms of kidney diseases and dual blockade of CCL2 and CXCL12 leads to additive effects on the in prevention of progression of nephropathy and proliferative lupus nephritis." (PMID 39492831, 2024). "Stromal-derived factor-1 (SDF-1), also known as CXCL12, and its receptor, the CXCR4 axis, is a crucial key pathway in cell trafficking during kidney damage." (PMID 35056905, 2021).
lupus nephritis (7 papers, 2018 to 2026). Glomerulonephritis in the context of systemic lupus erythematosus. "To elucidate the role of CXCL12/CXCR4 axis in lupus nephritis, we assessed CXCL12 expression in renal tissues at different disease stages." (PMID 41601976, 2026). "Biopsies of lupus nephritis and cutaneous lupus skin demonstrate increased CXCL12 levels correlated with disease severity." (PMID 39070795, 2024). "However these data contradicted some findings dealing with CXCL12 expression, which was found to be up-regulated in tubules and glomeruli of patients with lupus nephritis." (PMID 34744730, 2021). "Beside their chemotactic effects, PGD2 and CXCL12 are known to modulate basophil activation by FcεRI crosslinking, which may occur in active lupus nephritis patients through autoreactive IgE26,27." (PMID 29463843, 2018). "Combined DPP-4 and CXCL12/CXCR4 axis inhibition synergistically enhanced podocyte protection and attenuated renal inflammation, fibrosis, and oxidative stress in lupus nephritis." (PMID 41601976, 2026).
nasopharyngeal carcinoma (7 papers, 2014 to 2023). A carcinoma arising from the nasopharyngeal epithelium. "In nasopharyngeal carcinoma (NPC) cells, CXCL12 effectively attracted CXCR4+ Treg cells." (PMID 37497001, 2023).